STK11 (serine/threonine kinase 11)
Diseases named in the same sentence as STK11 in open-access papers (continued):
Sharing a sentence is not in itself a finding about the gene and the disease.
tumor (continued). "In contrast, the co-occurrence of the STK11 and KEAP1 mutations appear to drive resistance to ICIs, even in tumors with a high tumor mutational burden (TMB), by shaping an immunosuppressive metabolic environment that impairs immune cell activation." (PMID 40710207, 2025). "We are aware of one case study in the literature in which a woman with a germline PV in STK11 was diagnosed with a TNBC, in which the tumor showed loss of homologous normal allele." (PMID 40317347, 2025). "In contrast, tumor mutational status, particularly mutations in driver genes such as EGFR, KRAS, and STK11, has recently emerged as a more stable predictor of immunotherapy response." (PMID 40777022, 2025). "Plasma CXCL1 levels fail to be a biomarker; however, our results confirmed that tumor-derived STK11 plays a pivotal role in regulating cytokine secretion, thereby contributing to the modulation of the tumor–immune microenvironment." (PMID 41051525, 2025). "The tumor suppressor STK11/LKB1 activates AMPK, a central metabolic sensor that integrates energy stress signals through cross-talk with PI3K, mTOR, and MAPK pathways." (PMID 41179661, 2025). "This indication suggests the potential role of PEBP1/STK11 co-expression in tumor suppression or altered metabolic regulation in hypoxic conditions." (PMID 40806276, 2025). "Alterations in several tumor genes, such as mutations in KRAS, STK11, and KEAP1, have been suggested as potential biomarkers for the ICI response in patients with NSCLC." (PMID 39037971, 2024). "In a third case, when considering only the primary tumor sequencing data, CRUK0995 had a truncal driver mutation in the tumor suppressor gene STK11 (p.P179L)." (PMID 38821942, 2024). "Although the LKB1-independent roles of STRAD and MO25 in tumorigenesis are poorly understood, the tumor-suppressive activity of LKB1 is well known, as inactivating STK11 mutations are routinely detected in lung tumor biopsies." (PMID 39594681, 2024). "It’s also found that patients with extra-thoracic recurrence had lower tumor expression of STK11 than those with intrathoracic recurrence." (PMID 38736875, 2024). "Peutz–Jeghers syndrome (PJS) is an autosomal dominant disease caused by mutations of the serine-threonine kinase 11 (STK11/LKB1) gene, a tumor suppressor gene that determines hamartomatous gastrointestinal polyposis and typical mucocutaneous pigmentation." (PMID 39202722, 2024).
tumor (continued). "STK11 is a tumor suppressor and a negative regulatory factor as target of rapamycin signaling in mammalians." (PMID 38736875, 2024). "The mutation or loss of STK11/LKB1, RB1, TET2, GULP1, and CDKN2A107 expression also results in severe malignant conditions by altering the tumor immune microenvironment." (PMID 39201585, 2024). "STK11 functions as a tumor suppressor and is involved in several pathways that control cell growth and apoptosis." (PMID 38338763, 2024). "The results indicated that the PD-L1-negative, TMB-low, STK11-mutated, and KEAP1-unmutated groups demonstrated greater tumor reduction than the other groups." (PMID 38611005, 2024). "Serine/threonine kinase 11 (STK11) is a tumor suppressor gene, and loss-of-function mutations in this gene have been associated with enhanced tumor escape, invasion, and metastasis." (PMID 38983267, 2024). "PDE4 inhibitor Roflumilast inhibited STK11-KO cell migration and tumor size, further demonstrating that PDEs are essential for STK11-deficient cell migration." (PMID 38461159, 2024). "This aberrant activity is driven by various oncogenic pathways and dysfunctions in tumor suppressors, including mutated or amplified EGFR, PI3K, Akt, Ras, and Raf, as well as impaired PTEN, APC, LKB1/STK11, and Gator1." (PMID 38560690, 2024). "For example, both IL-6 and CXCL8 are reported to be elevated in KRAS-driven STK11-null LUADs and proposed to promote tumor immune evasion." (PMID 37968341, 2024). "Given our findings that STK11 knockout (KO) decreases EOC spheroid cell viability and tumor burden in mice, we proposed that disrupting spheroid formation by downregulating LKB1 and STRAD would impair the metastatic properties of human EOC cells." (PMID 39594681, 2024). "The work we present situates the HIPPO/YAP1 axis as a signaling cascade downstream of STK11 that modulates tumor-intrinsic cytokine expression." (PMID 37968341, 2024). "STK11 (Serine/threonine kinase 11), located on chromosome 19, is part of the serine/threonine kinase family of proteins and acts as a tumor suppressor." (PMID 39274207, 2024). "It enhanced the anti-tumor effects of programmed cell death protein 1 (PD-1) inhibitors in serine/threonine kinase 11 (STK11) mutant non-small cell lung cancer (NSCLC) through an axis inhibition protein 1 (AXIN1)-dependent manner." (PMID 39308524, 2024). "In summary, the current study demonstrated that metformin promotes anti-tumor immunity in STK11 mutant NSCLC in an AXIN1-dependent manner through the upregulation of multiple nucleotide metabolites." (PMID 39308524, 2024). "Regarding this, metformin restores AMPK-dependent signaling, leading to inhibition of tumor cell proliferation, but further prospective studies exploring its role in STK11-mutant NSCLC are warranted." (PMID 37490263, 2024). "It’s demonstrated that typical tumor suppressive effect of STK11 involved the activation of AMPK-related kinases reckoned as major regulators of cell survival under conditions of stress." (PMID 38736875, 2024). "STK11 is a tumor suppressor involved in cell motility and metabolism and NFE2L2 plays a key role in oxidative stress response, while PTP4A1 has been recently identified as a novel therapeutic target in cancer." (PMID 38191367, 2024).
tumor (continued). "For serine metabolism, LKB1 to LKB1/AMPK signaling and inactivation of STK11/LKB1 lead anti-tumor efficacy in NSCLC." (PMID 38841622, 2024). "STK11 adnexal tumours are usually present in an adnexal location and show diverse architectural patterns, a common association with PJS and recurrent STK11 alteration." (PMID 38376618, 2024). "The inactivation of STK11 gene or its protein product LKB1 is related to the cold tumor immune environment, which is accompanied by the decrease of infiltrating cytotoxic CD8+ T lymphocytes in both human tumors and genetically engineered mouse models." (PMID 38736875, 2024). "In vitro and in vivo studies have demonstrated that co-occurring mutations of STK11 and KEAP1 in KRAS-mutant NSCLC promote tumor growth and confer enhanced resistance to radiotherapy." (PMID 37675220, 2023). "Our studies also provide CC treatment paradigms by targeting the tumor microenvironment or molecules downstream of STK11/LKB1, with the goal of improving patient survival and quality of life." (PMID 37092555, 2023). "STK11/LKB1 is a kinase that acts upon the master metabolic regulator AMPK and other AMP-related kinases while permitting immune cell changes in tumor microenvironments when mutated in tumor cells." (PMID 37092555, 2023). "Deletions of 9p21.3, 9p24, STK11 and KEAP1 are associated with an immunologically ‘cold’ tumor microenvironment and immunotherapy resistance." (PMID 37875494, 2023). "Having identified STK11/LKB1 as a gene variant that supports CC development also provides new opportunities to identify STK11/LKB1 immune and metabolic influences on tumor and host biology." (PMID 37092555, 2023). "Deletion of serine/threonine kinase 11 (Stk11) in mouse ECs resulted in severe reductions of mature DC numbers and spontaneous tumor formation, indicating the crucial role of DCs in suppressing tumorigenesis." (PMID 37666809, 2023). "In the 1990s, STK11 (serine threonine kinase 11) was identified as a significant tumor suppressor gene." (PMID 36909198, 2023). "The lentivirus-enabled creation of the STK11/LKB1-knockout line led to decreased tumor growth compared with the lentivirus-enabled creation of the GFP control line in the NOD/SCID immunodeficient model, consistent with the observations of other groups." (PMID 37092555, 2023). "In this study, a link between STK11 mutations and decreased M1 macrophages was found in LUAD tumor tissues." (PMID 37506141, 2023). "Tumor immune microenvironment, systemic, and host tissue changes in mice bearing human STK11/LKB1-silenced tumors." (PMID 37092555, 2023). "As a first approach, it will be important to demonstrate that STK11/LKB1 is acting through AMPK or its other substrates to induce the changes in the tumor microenvironment potentially supportive of adipose and muscle wasting." (PMID 37092555, 2023). "Overall, our studies highlight the role of STK11/LKB1 in regulating CC development and as a potential tumor-specific CC biomarker." (PMID 37092555, 2023). "STK11 is also a central regulator of tumor metabolism through the regulation of HIF-1α-dependent metabolic reprogramming." (PMID 37351538, 2023). "It was revealed that STK11 mutation affected CD1E expression to regulate macrophage differentiation in LUAD and then promote tumor progression." (PMID 37506141, 2023).
tumor (continued). "Here, we validated the two tumor suppressor genes, STK11 and NF2, involved in the mTOR signaling pathway which have been suggested as promising oncogenic therapeutic targets in recent studies." (PMID 37351538, 2023). "The observation suggested that STK11 mutation reduced cellular infiltration in M1 macrophages, apoptosis, and the AMPK signaling pathway that promoted tumor growth." (PMID 37506141, 2023). "Collectively, these studies verified that tumors which induce cachexia in vivo because of STK11/LKB1 silencing display changes in their tumor immune landscapes similar to observations made by other groups in NSCLC tumors enriched for STK11/LKB1 alterations." (PMID 37092555, 2023). "In parallel, STK11 inactivation facilitates tumor growth by inducing an immunosuppressive TME, a process where STING (STimulator of INterferon Genes) plays a key role." (PMID 37370686, 2023). "The deficiency of serine/threonine protein kinase 11 (STK11), one of the most common tumor suppressor genes in non‐small‐cell lung cancer, is a crucial player in tumor immune microenvironment regulation." (PMID 37506141, 2023). "Previous studies have shown that STK11 was an upstream kinase involved in AMPK activation and associated with the inhibition of tumor cell epithelial‐mesenchymal transition through the p38‐mitogen‐activated protein kinase (MAPK) signaling pathway." (PMID 37356061, 2023). "STK11 mutations are frequently found as inactivators of tumor-suppressor genes in NSCLC, and encode liver kinase B1 (LKB1), a protein that suppresses cell growth and metabolism." (PMID 36672698, 2023). "Inactivation of STK11 signaling stimulates cancer cells to produce G-CSF, CXCL7, IL-6, and IL-1β, thereby recruiting tumor-associated neutrophils, which results in suppression of cytotoxic T-cell activity." (PMID 37265800, 2023). "Analysis of ctDNA from 246 NSCLC patients validated the association between cancer-associated weight loss at tumor diagnosis and STK11/LKB1 variants." (PMID 37092555, 2023). "STK11 is a tumor suppressor gene, which can encode kinase B1 in liver (LKB1), and pathway regulated by which was highly associated with tumor suppression in AML." (PMID 37367950, 2023). "In patients with NSCLC, alteration of KRAS/STK11 was found to have influence on tumor microenvironment and decrease PD-L1 expression levels, suggesting a lower response rate to ICIs and poorer prognosis 70,71." (PMID 35069896, 2022). "This article reviews the role of PD-L1 expression, tumour mutational burden (TMB), smoking history, STK11/KEAP1 mutations and the gut microbiome as predictive markers for immunotherapy." (PMID 35200543, 2022). "KRAS/STK11 aberrations, on the other hand, promote a so-called ‘cold tumor’ immune microenvironment, generally with limited PD-L1 expression and reduced infiltrating CD8+ T cells." (PMID 36077640, 2022). "Liver kinase B1 (LKB1) is a tumor suppressor involved in the control of cell response to DNA damage, encoded by STK11, a gene that is mutated in Peutz–Jeghers syndrome and in uncommon cancers." (PMID 36428727, 2022). "Due to STK11 role as a tumor suppressor, patients with PJS also possess a significant risk for developing an array of malignancies including colorectal, breast, gastric, small bowel, pancreatic, ovarian, cervical, lung, thyroid, and gonadal tumors." (PMID 35685436, 2022). "Patient L2 TB and CDX presented a KRAS-mutant tumor with concurring mutations in genes KEAP1, STK11, and RBM10." (PMID 35511434, 2022).
tumor (continued). "In this paper, the current status of PDL-1 expression on tumour cells, the smoking status of patients, tumour mutational burden, gut microbiome and STK11 and KEAP1 mutations in the tumour as predictive biomarkers for PD(L)-1-based immunotherapy are summarized." (PMID 35200543, 2022). "Mutations in oncogenes, such as KRAS; and subsets of loss-of-function mutations in tumor suppressors, such as FBXW7 or STK11, can cause resistance to DNA damage based therapies." (PMID 35477555, 2022). "The expression levels of MYC, NR5A2, SNAI1, TWIST1, and STK11 were significantly higher in tumor-adjacent tissues than in the matched EC samples, and this difference was not influenced by the content of cancer cells in cancer-adjacent tissues." (PMID 36140779, 2022). "STK11 (also known as LKB1) has been identified as a tumor suppressor in multiple cancers, but in EC, clinical samples have not been evaluated in this respect." (PMID 36140779, 2022). "Tumor mutational burden (TMB) was also evaluated considering different cut-offs, and we found a significant association between TMB and STK11 and KRAS mutations." (PMID 35625958, 2022). "We demonstrated that in EC, tumor STK11 expression level was lower than in the matched TA and in Ctrl samples." (PMID 36140779, 2022). "STK11 mutations in NSCLC may be associated with worse outcomes with ICIs since the inactivation of this serine threonine kinase involved in various cellular functions is associated with a low T lymphocytes tumor infiltration and a “cold” tumor microenvironment." (PMID 35515125, 2022). "The liver kinase B1 (LKB1/STK11) is a tumor suppressor that acts via the activation of AMP-activated protein kinase (AMPK)." (PMID 35832432, 2022). "Targeting of Stk11 also led to the establishment of KRT5+/TTF1– tumors, indicating that loss of this tumor suppressor leads to the simultaneous development of NSCLC-SCC and NSCLC-ADC." (PMID 33738287, 2021). "Histone deacetylase 11 (HDAC11) inhibits histone acetylation of serine/threonine kinase 11(STK11) promoter to inhibit its transcription, thereby, promoting the glycolysis pathway and leading to tumor stemness." (PMID 35004688, 2021). "For example, tumours with KRAS/STK11 comutation commonly have a tumour microenvironment (TME) with poor immune response, lacking CD8 + tumour-infiltrating lymphocytes but including an abundance of T regulator cells." (PMID 34776511, 2021). "Some are accounted for among the characteristic mutations by well-known oncogenes and tumor suppressors, such as NRAS, STK11/LKB1, and PREX2, and several genes associated with tumor processes, CDK12 IKBKB and RP1L1." (PMID 34884942, 2021). "STK11, formerly called Liver Kinase B1 (LKB1), encodes an important tumor suppressor that regulates numerous intracellular signaling networks impacting metabolism, proliferation and cell morphology." (PMID 34849607, 2021). "KRAS/STK11/KEAP1 co-mutated tumors are characterised by a lower PD-L1 expression and few tumor infiltrating lymphocytes (TILs), leading to a less immune-sensitive TME." (PMID 34944952, 2021). "Intriguingly, T1 and T3 of HCC10 showed distinct branches for these two tumor regions possessed different mutational loci in TSC2, even though they shared a common ancestor in mutations including AXIN1, STK11 and TERT." (PMID 34211467, 2021). "The canonical tumor-suppressive role for STK11/LKB1 involves the activation of AMPK-related kinases, a master regulator of cell survival during stress conditions." (PMID 34831355, 2021).